KDM5C (lysine demethylase 5C)
Diseases named in the same sentence as KDM5C in open-access papers (continued):
Sharing a sentence is not in itself a finding about the gene and the disease.
tumor (continued). "In contrast, depleting YY1 in low KDM5C-expressing tumor cells completely eliminated chromatin-bound YY1 and promoted tumor regression." (PMID 39433896, 2024). "A study found that KDM5C, a histone H3K4-specific demethylase, can repress FASN-mediated lipid metabolism to exert tumor suppressor activity in ICC." (PMID 38648205, 2024). "In a recent study, KDM5C was significantly upregulated in HCC in vitro, and silencing of KDM5C reduced the malignant behaviors of the cell lines and inhibited tumor growth in nude mice." (PMID 37185761, 2023). "It has also been found that tumor driver genes IDH1/2, JARID1C/KDM5C and UTX/KDM6A can regulate histone demethylation and thus affect cancer metabolism and tumor progression." (PMID 36941564, 2023). "Overall, our results highlight the role of KDM5C in GBM, identifying the new hypoxia-induced signature exclusively localized in the tumor tissue." (PMID 36142158, 2022). "KDM5C restoration markedly inhibited the RCC4 tumor cell growth in NOD/SCID mice, while the administration of Lip-1 restored the tumor formation." (PMID 34522206, 2021). "It is likely that other ccRCC-relevant epigenetic tumour suppressors such as BAP1, SETD2, and KDM5C also influence HIF-α transcriptional outputs." (PMID 32807776, 2020). "Frozen tumor tissues and plasma were used to measure PBRM1, BAP1, SET domain-containing 2 (SETD2), KDM5C, FOXC2, CLIP4, AQP1, DDX11, BAIAP2L1, and TMEM38B mRNA levels, and correlation with the Fuhrman grade was investigated." (PMID 32392781, 2020). "Consistent with this research, in the present study we showed that overexpression of KDM5C promoted HCC cells proliferation and enhanced tumor formation in vivo." (PMID 26503415, 2015). "One study observed elevated expression of KDM5C and HIF-1α at GBM tumor margins." (PMID 40450300, 2025). "Furthermore, simultaneously targeting KDM5C and YY1 effectively inhibited tumor growth in KDM5C-proficient tumor cells." (PMID 39433896, 2024). "PFDN5, a known negative regulator of c-Myc and thus a potential tumor suppressor, exhibiting a remarkable negative correlation with KDM5C expression, ranking second in correlation coefficient, was consequently chosen for subsequent analysis." (PMID 38216914, 2024). "One landmark study demonstrated six tumour-suppressor genes that escape XCI and may contribute to cancer sex-disparity (ATRX, CNKSR2, DDX3X, KDM5C, KDM6A, and MAGEC3)." (PMID 37759468, 2023). "When examining CaSki cells, which are HPV16-positive tumor cells, it becomes apparent that they exhibit lower levels of KDM5C compared to tumor cells lacking HPV infection." (PMID 38067286, 2023). "Interestingly, fluorescence-guided surgery on GBM sections further revealed higher KDM5C and HIF1A levels in the tumor rim niche compared to the adjacent tumor margin, indicating a regionally restricted hyperactivity of this regulatory axis." (PMID 36142158, 2022). "Overall, the in vitro data on the GBM tumor cell line indicate that, in hypoxic conditions, high levels of p75NTR may correlate with high levels of HIF1A and KDM5C, a negative regulator of BDNF." (PMID 36142158, 2022). "Since GBM contains several tumor microenvironments (TMEs) with irregular distributions of signaling networks, we wondered whether the gene expression levels of KDM5C, BDNF, and HIF1A differed in distinct GBM tumor areas." (PMID 36142158, 2022). "The controversy about KDM5C and ZMYND8's function in tumorigenesis might be due to the different role they play in different stages of tumor." (PMID 33977073, 2021). "Furthermore, evidence of parallel evolution was demonstrated for multiple tumour suppressor genes (SETD2, PTEN, KDM5C), suggesting selective pressures drive inactivation of the same gene multiple times within a single tumour." (PMID 34459009, 2021).
tumor (continued). "A prospective study examining frozen tissue qRT-PCR of AQP1, DDX11, BAIAP2L1, and six previously identified genes (PBRM1, BAP1, SETD2, KDM5C, FOXC2, and CLIP4) showed that expression of DDX11 was a significant factor for predicting tumor aggressiveness based on Fuhrman grade." (PMID 31963294, 2020). "There were no direct differences for gender, pathological type, and tumor stage between the high and low KDM5c expression groups." (PMID 33042830, 2020). "The KDM5 subfamily (also known as JARID1 subfamily) consists of four members, KDM5A (JARID1A), KDM5B (JARID1B), KDM5C (JARID1C) and KDM5D (JARID1D) whose deregulation in various kinds of cancer has been widely documented to contribute significantly to tumor initiation and progression." (PMID 31060229, 2019). "For instance, KDM5C is induced by HIF, and its demethylase activity against global H4K4me3 mark is dependent on HIF in VHL-/-ccRCC cells, and yet it clearly plays an anti-tumor role in ccRCC." (PMID 30355451, 2018). "In the same tumor, distinct mutations at different parts of the tumor could inactivate the same tumor suppressor genes such as SETD2, Phosphatase And Tensin Homolog (PTEN), and Lysine Demthylase 5C (KDM5C/JARID1C)." (PMID 28445125, 2017). "Gene mutations (KDM5C and SETD2) that were highly correlated with ccRCC tumor size were not significantly correlated with survival (data not shown)." (PMID 26848523, 2016). "The tumor with the most mutated genetic landscape contained a shared SETD2 mutation and four nonshared mutations (in genes KDM5C, BAP1, and PBRM1)." (PMID 25124064, 2014). "KDM5A and KDM5B have been indicated to be carcinogenic in numerous studies, while KDM5C and KDM5D may function as tumor suppressors, although the evidence is conflicting which may be due to the specific tumor microenvironment and different experimental conditions." (PMID 38769556, 2024). "In addition, higher expression of ATRX, DDX3X, KDM5C and KDM6A was observed in female patients, indicating that tumor-suppressor genes that escape from X-inactivation may contribute to HCC sex bias." (PMID 36118521, 2022). "Molecular alterations in RCC tumors have been extensively studied in the last decade, especially in ccRCC but neither identified mutations (e.g.,: VHL, BAP1, PBRM1, SETD2, KDM5C, MTOR) nor transcriptome-based ccRCC tumor sub-classification have straightforward clinical relevance." (PMID 33535553, 2021). "Recent study showed that HIF1α was essential for tumor formation and HIF-1α regulates glycolysis 31, our data further supported the notion that KDM5C partially inhibited the elevated expression of HIF1α- and metabolism-related genes, which may be caused by loss of VHL." (PMID 34522206, 2021). "In addition, evidence suggests that HIF-induced KDM5C is tumor-suppressive, and this constitutes a negative feedback loop in regard to tumor growth." (PMID 30355451, 2018). "Since ISGF3 is activated by HIF and suppressed after the loss of PBRM1, KDM5C, SETD2 or BAP1, it may function as the executioner of a negative feedback loop that potently opposes tumor growth." (PMID 30355451, 2018). "Since the suppression of PBRM1, KDM5C, SETD2 or BAP1 all lead to the reduction of ISGF3, a potent tumor suppressor, it is possible that any effective therapeutic intervention that restores ISGF3 function could benefit ccRCC patients with a wide variety of mutations." (PMID 30355451, 2018). "In addition, KDM5C knockdown in VHL−/− cell lines has been shown to significantly increase tumorigenesis in a xenograft model of RCC, thus adding further evidence for a tumor suppressive role of KDM5C in ccRCC." (PMID 28812986, 2017). "Interestingly, we observed the loss of histone lysine demethylases KDM5C and KDM6A in NATs but not in tumor tissues, suggesting that the absence of these enzymes might be linked to the initiation of BTC development." (PMID 41301905, 2025).
tumor (continued). "Therefore, the reduced tumor growth in mouse xenografts is not a result of the differential proliferation of these cells as shown by the unaltered Ki-67 expression in PC3 and KDM5C knockdown cells." (PMID 35454801, 2022).
cancer (83 papers, 2010 to 2026). A tumor composed of atypical neoplastic, often pleomorphic cells that invade other tissues. "Across all human cancer types, KDM5C mutations arise most frequently in endometrial, renal and lung tumours." (PMID 39955388, 2025). "Considering the definition of synthetic lethality and the results presented here, we propose that KDM5C and YY1 form a synthetically lethal gene pair, providing a rationale for the clinical treatment of patients with KDM5C-deficient cancer by targeting YY1." (PMID 39433896, 2024). "TCGA has identified KDM5C mutation as a cancer driver mutation in the genes encoding the histone demethylases." (PMID 33324444, 2020). "Other epigenetic modifiers were also associated with high levels of ITH in KIRC (e.g., PBRM1 or KDM5C), but correlated with lower heterogeneity in a pan-cancer analysis or in other cancer types." (PMID 30897760, 2019). "KDM5C is known to be associated with X-linked mental retardation and is also involved in the development of cancer." (PMID 30522514, 2018). "KDM5C is frequently mutated or aberrantly expressed in various cancer types." (PMID 39433896, 2024). "Lysine demethylase 5C (KDM5C) has been implicated in the development of several human cancers." (PMID 38216914, 2024). "KDM5C has been shown to be frequently mutated or aberrantly expressed in various cancers." (PMID 39433896, 2024). "Notably, ETV4 has numerous implications as an adverse prognostic factor in multiple cancer types, including ccRCC, which is prominently associated with KDM5C mutations." (PMID 36631623, 2023). "Interestingly, KDM5C has been shown to be one of the X-chromosome genes that escapes from X-inactivation and to be more frequently mutated in males, suggesting that sustained KDM5C expression is part of the reason for the reduced cancer incidence in females." (PMID 35805040, 2022). "In addition to mutations, alterations in the KDM5C expression levels have been related to the development of various cancers." (PMID 36142158, 2022). "Despite KDM5c is associated with a variety of cancer types, the function of KDM5c in the progression of BC is largely unknown." (PMID 35248043, 2022). "Similarly, its interaction with JARID1D or KDM5C suppresses the activation of metastasis-linked genes in various cancers." (PMID 36064715, 2022). "To evaluate the effects of these cancer-related KDM5C mutations on glycogen accumulation and ferroptosis, we selected several JmjN and JmjC domains associated-missense mutations and constructed the corresponding RCC4 cell lines that stably expressed the mutant proteins." (PMID 34522206, 2021). "Moreover, KDM5C has been studied with regard to its significance in X-inactivation and has been associated with certain types of cancer." (PMID 30522514, 2018). "Furthermore, KDM5C promotes proliferation of cancer cells, and knockdown of KDM5C causes a significant delay in the G1/S transition." (PMID 26503415, 2015). "In HCC, the histone demethylases KDM5C and JARID1B are highly expressed in aggressive cancer cells, with their expression levels closely associated with distant metastasis." (PMID 40699663, 2025). "KDM5C, a histone demethylase, mediates changes in chromatin structural remodeling in tumors and has both stimulatory and inhibitory effects on various cancer cell types." (PMID 40629546, 2025). "This study shows that KDM5C binds to YY1, that it facilitates YY1 chromatin recruitment, and that targeting YY1 increases the vulnerability of KDM5C-low cancer cells." (PMID 39433896, 2024). "KDM5C also bound to the promoters of genes that encode extracellular matrix proteins such as ITGB1 and ITGB1-DT, which have been implicated in cancer progression." (PMID 38383780, 2024).
cancer (continued). "In summary, our work demonstrates a synthetic lethal interaction between YY1 and KDM5C and suggests combination therapies for cancer treatments." (PMID 39433896, 2024). "A synergistic antitumor effect is exerted when both KDM5C and YY1 are depleted, and targeting YY1 appears to be a vulnerability in KDM5C-deficient cancer cells." (PMID 39433896, 2024). "Studies have shown that abnormal expression of KDM5C is closely related to the occurrence and development of various cancers." (PMID 35248043, 2022). "KDM5C has been reported to be highly expressed in various cancer cell types, particularly in primary PCa." (PMID 35454801, 2022). "To investigate the roles of TRIM11 and KDM5C in cancer cells, we first constructed stable expressed cell lines of TRIM11 and KDM5C in MDA-MB-231." (PMID 36192394, 2022). "These suggest that TRIM11 regulates H3K4me3 on enhancers of cancer-related genes through targeting KDM5C." (PMID 36192394, 2022). "There is an interaction between KDM5C and histone deacetylases (HDACs), which have been successfully targeted in cancer therapy, consistent with the results of our protein interaction analysis." (PMID 35493099, 2022). "In contrast, KDM5C has also been shown to be overexpressed and to function as an oncogene in some cancers." (PMID 35805040, 2022). "A histone demethylase named KDM5C activates estrogen/estrogen receptor alpha‐target genes to promote cancer cell growth, while suppresses type I interferons and interferon‐stimulated genes to escape from immune surveillance." (PMID 33977073, 2021). "Previous studies reported that genetic alterations of KDM5C were common in various types of cancers including breast, colon, ovarian, prostate cancer and so on." (PMID 33953726, 2021). "Collectively, the pan-cancer predictive significance of KDM5C alterations and its complementation to MSI-H in ICI therapy are anticipated." (PMID 33953726, 2021). "KDM5C plays a significant role in the tumorigenesis, cancer cell proliferation, invasion, metastasis and drug resistance." (PMID 33953726, 2021). "Here, we performed this pan-cancer analysis to investigate KDM5C alterations frequency and their predictive significance for ICIs treatment outcomes across cancer types." (PMID 33953726, 2021). "Among these, KDM5C (lysine demethylase 5C) has been reported to have a significant role in transcriptional regulation of cancer cells in concert with ZMYND824,26." (PMID 33323928, 2020). "In the aspect of cancer, KDM5C has both oncogenic and anti-oncogenic properties like a double-edged sword." (PMID 32714863, 2020). "Inhibition or depletion of KDM5B and KDM5C led to increased STING expression in a wide range of cancer cells." (PMID 30080846, 2018). "KDM5C or SETD2 in ccRCCs have been associated with advanced stage, grade and possibly worse cancer-specific survival." (PMID 26848523, 2016). "All escapees (normal or “cancer-specific”) showed low levels of DNA methylation at their promoters (e.g., KDM5C, HDAC8)." (PMID 25653311, 2015). "Previous studies have shown that KDM5C plays diverse roles in cancer progression." (PMID 39433896, 2024). "This research indicates that RACK7 and KDM5C may play a role in inhibiting the occurrence of cancer." (PMID 38769556, 2024). "Considering the reported association between c-Myc signal transduction and autophagy inhibition during cancer progression, we hypothesized that KDM5C/PFDN5 might influence the autophagy activity of CRC cells." (PMID 38216914, 2024). "KDM5C, as a cancer driver gene in HCC, could have crosstalk of histone demethylation and metabolic reprogramming." (PMID 37185761, 2023). "Interestingly, many genes related with epigenetic regulation of enhancer activity are frequently mutated in cancer, such as MLL3/4, p300, CBP, lysine demethylase 6A (KDM6A, also named as UTX) and lysine demethylase 5C (KDM5C)." (PMID 36192394, 2022). "KDM5C is a histone H3K4 demethylase and frequently mutated in several types of cancer." (PMID 36192394, 2022).
cancer (continued). "This study provides additional strong evidence for the role of KDM5C in promoting cancer." (PMID 35493099, 2022). "The dual activator and repressor nature of KDM5C together contributes to cancer development." (PMID 33977073, 2021). "Meanwhile, KDM5C was found to repress a large cohort of genes, among which the type I IFNs and ISGs were the most enriched, suggesting that KDM5C might protect cancer cells from immune surveillance by restraining these genes from expression." (PMID 33977073, 2021). "SETD2 encodes a methyltransferase that specifically trimethylates lysine-36 of histone H3 (H3K36me3), whereas KDM5c (also known as JARID1C) is a gene that encodes an H3K4me2/3 demethylase that plays a central role in transcriptional repression and can mediate cancer progression." (PMID 34439859, 2021). "Collectively, KDM5C alterations could be considered as a potential pan-cancer predictive biomarker for ICI treatment, especially for NSCLC." (PMID 33953726, 2021). "Notably, cancers with KDM5C alterations also had the higher TMB level than those without these alterations (12 vs. 6 mut/Mb, P < 0.0001)." (PMID 33953726, 2021). "Although KDM5C is assumed to protect females from the onset of cancer and has been shown to affect the instability of the heterochromatin genome in ccRCC 15, its exact role in ccRCC is still largely unknown." (PMID 34522206, 2021). "Moreover, the expression levels of 13 out of 16 genes (except RGPD8, NPR3, and KDM5C) differed according to the cancer stage." (PMID 31963294, 2020). "KDM5c abnormality was subsequently correlated with development of various cancers." (PMID 33042830, 2020). "This is opposite to the way KDM5c regulates the c-Jun protein, suggesting different mechanisms may allow different functions of KDM5c in different cancer types." (PMID 33042830, 2020). "To investigate the mechanism underlying KDM5c regulation of RKO/HCT-8 cell growth, we used quantitative PCR (qPCR) and Western blot methods to examine changes of multiple cancer-related genes at the transcription and protein level when KDM5c expression was altered." (PMID 33042830, 2020). "Despite these associations with various cancers types, the function of KDM5c in CRC progression has not been reported." (PMID 33042830, 2020). "Specific cancer genes can also have sex-biased patterns of somatic mutation, including the lower frequency of KRAS mutation among males with colorectal cancer, higher mutation frequency of PBRM1 and KDM5C in males and BAP1 in females with renal carcinoma." (PMID 33330090, 2020). "Our observations concur with the expected expression profiles in the two normal and three cancer cell lines, i.e., KDM5C is expressed from all X chromosome fragments that carried the gene, and HUWE1 is expressed only from the non-XIST RNA-coated X fragments that carried it." (PMID 25653311, 2015). "For example, in our study HRAS (P = 5.0 × 10-46), AKT1 (P = 9.5 × 10-26), PIK3CA (P = 5.5 × 10-5), B2M (P = 6.7 × 10-4), and KDM5C (P = 3.5 × 10-3) were predicted to be putative cancer genes using Fisher’s exact test and evidently designated as cancer driver genes according to the 20/20 rule." (PMID 25360158, 2014). "To investigate whether transcriptional changes might underlie the different effects of KDM5C and KDM5D mutation on cancer cell behaviours, we conducted RNA-seq of triplicate samples of all 8 mutant 786-O cell populations and identified up- and down-regulated genes compared to sgCtrl cells." (PMID 39955388, 2025). "They identified KDM5C and KDM6A as the EXITS (escape from X-inactivation tumor suppressors) genes and suggested that mutations in EXITS genes could underlie the male predominance in various cancers." (PMID 38982123, 2024). "Cancer Genome Atlas (TCGA) pan-cancer analysis suggested that the association of KMT2C/BCOR/KDM5C mutations with ICB response observed here might not result from DNA repair defects." (PMID 35681795, 2022).